CD4 (CD4 molecule)
Diseases named in the same sentence as CD4 in open-access papers (continued):
Sharing a sentence is not in itself a finding about the gene and the disease.
T-LGL leukemia (continued). "By flow analysis, we observed that 68 out of 101 patients (67.3%) were characterized by classical CD3+/CD8+/CD4- expression (CD8+ T-LGL leukemia), while the remaining 33 patients (32.7%) were distributed among CD3+/CD4+/CD8+dim (n = 23, 22.8%) and CD3+/CD4+/CD8- (n = 10, 9.9%) phenotypes." (PMID 28977911, 2017). "Taken together, this is the first case of aggressive T-LGL leukemia with phenotype of TCRαβ and CD4-/CD8- which shows a CNS involvement during chemotherapy and responded well to T-PEPC metronomic regimen, suggesting that metronomic regimen should be a better treatment option for such patients." (PMID 28427176, 2017). "The typical phenotype of T-LGL leukemia is CD3+/TCR-αβ+/CD4-/CD8+/CD57+/ CD16+." (PMID 28427176, 2017). "Thus, an increase of CD3(+)/CD56(−) or CD3(−)/CD56(+) cells by peripheral blood flow cytometry and/or an inverted CD4(+)/CD8(+) cell ratio suggests the existence of LGL leukaemia." (PMID 22593689, 2012). "One is that CD4+ T-LGL leukemia is characterized only by STAT5B mutations and not STAT3 mutations." (PMID 36755813, 2022). "The T-LGL leukemia phenotype is typically CD3+, TCRαβ+, CD8+, CD16+, CD45RA+, and CD57+, and cells are CD4−, CD5dim, CD27−, CD28−, CD45RO−." (PMID 35646651, 2022). "A vast majority of patients (80%-90%) with T-LGL leukemia showed a CD3+ CD4-CD8+ CD57+ CD56- CD28-,TCRαβphenotype, while CD4- CD8- usually accompanied with TCR γδ, but had a favorable survival of 85% at 3 years." (PMID 28427176, 2017). "Bone marrow infiltration was typical for T-LGL leukemia, but T-LGL cells had the unusual phenotype (CD4+)." (PMID 18474096, 2008). "One study demonstrated that the disease course in the CD4+ T-LGL leukemia cohort is indolent, and none of the patients with STAT5b mutations appeared to require therapy during the observation period." (PMID 38610985, 2024). "Similarly, cases of CD4+ and γδ T cell T-LGL leukemia have been described previously, although their reported prevalence was lower than for CD8+ T-LGL leukemia." (PMID 37063893, 2023). "STAT3 mutations are generally found almost exclusively in CD8+ rather than CD4+ patients, and more specifically, CD8+ CD16+ CD56- T-LGL leukemia patients exhibit more STAT3 mutations." (PMID 35646651, 2022). "The difference of Fas ligand production observed on transcriptional expression was also confirmed by ELISA measuring Fas ligand level in patients’ plasma (CD16+/CD56- CD8+ T-LGL leukemia: 88.3 ± 14.18 pg/ml, the other CD8+ and CD4+ immunophenotypes: 16.08 ± 14.62 pg/ml, P < 0.0001)." (PMID 28977911, 2017). "For example, TCR Vβ usage has been studied on CD3+, CD4+, and CD8+ T cells in LGL leukemia patients, or in naïve, effector, and memory lymphocytes in healthy subjects, or in total CD4+ and CD8+, effector CD4+CD28+ and CD8+CD28+, and effector memory CD4+CD28−CD57+ and CD8+CD28−CD57+ cells in AA." (PMID 34572739, 2021). "Furthermore, TCRγδ+ T-LGL leukemia is mostly CD4-negative, partly CD8-positive, and approximately 50% show CD16 and CD56 expression." (PMID 28407008, 2017). "T-LGL leukemia is typically a disorder of CD8+ cytotoxic T cells, whereas the CD4+ (with or without CD8 coexpression) phenotype of T-LGL leukemia is uncommon." (PMID 36362126, 2022).
acute pancreatitis (18 papers, 2013 to 2025). An acute inflammatory process that leads to necrosis of the pancreatic parenchyma. "Recent studies on acute pancreatitis have demonstrated that the number of peripheral CD4+ T cells in the blood is reduced in patients with severe disease." (PMID 40560328, 2025). "Several studies have reported depletion of circulating lymphocytes in acute pancreatitis, especially CD4-positive lymphocytes." (PMID 24566874, 2014). "In our study, only third of patients were on HAART therapy and only 18 patients on PCP prophylaxis, suggesting other risk factors are contributing at least equally to the development of acute pancreatitis in patients with a low CD4." (PMID 23390470, 2013). "Interestingly, in the L‐arginine‐induced acute pancreatitis model, VB12 intervention attenuated acute pancreatitis while simultaneously increasing the proportion of Treg cell subtypes in CD4+ T lymphocyte." (PMID 39415850, 2024). "Among T-lymphocytes, CD4+ T-cells peripherally deplete to a greater extent than CD8+ T-cells in both moderate acute pancreatitis (MAP) and severe acute pancreatitis (SAP), due to their increased infiltration from blood vessels to the site of injury bordering acini." (PMID 32796685, 2020). "In addition, nicotine was found to reduce the severity of acute pancreatitis by controlling CD4+CD25+ regulatory T cells (Tregs)." (PMID 29870540, 2018). "The percentage of CD4+ lymphocytes expressing PD-1 and CD14+ monocytes expressing PD-L1 on day 1 and day 3 was higher in acute pancreatitis patients compared to healthy controls and higher in the IC group of acute pancreatitis patients compared to non-IC." (PMID 36010357, 2022). "CD4 + CD25 + CD127high cell at early phase of acute pancreatitis yields good specificity in detecting non-MOF at a suggested cutoff value 6.41%." (PMID 28174597, 2017). "In the progression of acute pancreatitis, inflammatory factors such as IL-6 and TNF-α drive neutrophil aggregation and release extracellular traps (NETs), exacerbating tissue damage, while inducing lymphocyte apoptosis (especially CD4+ T cells), leading to immune suppression." (PMID 41141256, 2025).
cervical disease (18 papers, 2005 to 2025). "Crude and adjusted odds ratios (ORs) for factors potentially associated with cervical disease progression and regression (adjusting for age, CD4 cell count, HIV RNA viral load, high‐risk HPV, cervical disease at baseline and precancer treatment)." (PMID 41194500, 2025). "In contrast, lower CD4 cell counts and high HIV RNA viral loads have been associated with increased cervical disease incidence and progression." (PMID 41194500, 2025). "Several studies showed that the level of CD4+ cell count is inversely associated with the risk of HPV infection and the development of cervical disease, and women with a high CD4+ cell count (>500 cells/L) had a similar risk as those without HIV infection." (PMID 36851143, 2023). "39.1% of women with prevalent anal HPV-16 currently smoked cigarettes, 78.3% had nadir CD4 count ≤200 cells/μL, 17.4% had concurrent prevalent cervical HPV 16, and 21.7% reported anogenital herpes in the past 6 months." (PMID 35587503, 2022). "Only two women in the entire cohort had three concurrent risk factors, and one of these two had prevalent anal HPV 16 (with low nadir CD4, prevalent cervical HPV 16 and recent anogenital herpes)." (PMID 35587503, 2022). "This study is the first to report a partial disconnect between absolute CD4 count and CD4 percentage with cervical disease." (PMID 32118737, 2020). "Additional results of CD4 percentage should be used concurrently with absolute CD4 count to monitor cervical disease in HIV-1-positive women." (PMID 32118737, 2020). "Cervical disease was more prevalent in women with low CD4 percentage than in women with high CD4 percentage, regardless of absolute CD4 count." (PMID 32118737, 2020). "Approximately, 68% (59/87) of HIV-1-positive women with different stages of cervical disease presented with a CD4 percentage below or equal to 28% and a median absolute CD4 count of 400 cells/μl (Inter quartile range, IQR, 300–500 cells/μl." (PMID 32118737, 2020). "It further suggests that other clinical immune cell markers apart from CD4 cells play a role in cervical disease progression." (PMID 32118737, 2020). "Sixty eight percent (59/87) of HIV-1-positive women with different stages of cervical disease presented with a CD4 percentage equal or less than 28%, and a median absolute CD4 count of 400 cells/μl (IQR 300–500 cells/μl)." (PMID 32118737, 2020). "There is also a novel association between low CD4 percentage and age (above 30 years) for HIV-1-positive women with ICC, where age was also significantly predictive of cervical disease stage." (PMID 32118737, 2020). "CD4:CD8 ratios varied widely across cervical disease stages." (PMID 33257839, 2021). "Our results show that both CD4 count > 350 cells/μl and CD4 percentage >28% did not appear to likely prevent the risk of any cervical disease stage (all P > .05)." (PMID 32118737, 2020). "Comparison between age of patients, CD4 status, and cervical disease in HIV-1-positive patients." (PMID 32118737, 2020). "The discordance between absolute CD4 count and CD4 percentage suggests that other lymphocytes apart from CD4 cells may play role in the development cervical disease." (PMID 32118737, 2020). "We next wished to determine whether there was any relationship between stage of cervical disease, age, CD4 cell levels and HIV-1 status." (PMID 32118737, 2020). "These inconsistencies regarding the effect of HAART and CD4+ cell counts on SILs on HIV-infected women suggest that additional immunologic factors may play a role in HPV-related cervical disease in suppression HPV." (PMID 24453469, 2013). "Previous studies demonstrated that pDCs could induce the differentiation of naïve CD4+ T cells to Treg cells when cocultured with cervical neoplastic keratinocytes, indicating the development of a tolerogenic response and interference of an antitumour immune response." (PMID 36967539, 2023).
cervical disease (continued). "However, it could be argued that HSV-2 infection contributes to cervical carcinogenesis by reducing CD4+ T-cell counts." (PMID 33824853, 2021). "Thus, using CD4 percentage may add a better prognostic indicator of cervical disease stage than absolute CD4 count alone." (PMID 32118737, 2020). "In particular, low CD4+ T-lymphocyte counts may increase the risk of recurrence, whilst higher CD4+ cell counts may promote HPV clearance, highlighting the role of immunity in the development of cervical disease." (PMID 29037188, 2017). "Comparison between CD4 status, HPV infection, and cervical disease stage in HIV-1-positive patients." (PMID 32118737, 2020). "Comprehensive investigation of low CD4 percentage with regard to HIV-1 and HPV viral loads in women with cervical disease is warranted in order to determine if this relationship is causal." (PMID 32118737, 2020). "Our study suggests the presence of a partial disconnect between absolute CD4 count and CD4 percentage in a subgroup of HIV-1-positive women histologically diagnosed with cervical disease." (PMID 32118737, 2020). "We characterized HPV genotypes within cervical tumor biopsies, assessed the relationships of cervical disease stage with age, HIV-1 status, absolute CD4 count, and CD4 percentage, and identified the predictive power of these variables for cervical disease stage in a cohort of South African women." (PMID 32118737, 2020). "HPV infection and cervical disease stage are irrelevant to the host immune status but cervical disease was more prevalent in women with low CD4 percentage regardless of absolute CD4 count that falls within the normal range." (PMID 32118737, 2020). "In this study, we have used CD4- and CD8-depleted populations of responder cells in an ELISPOT assay of IFN-γ release to screen directly ex vivo for both CD4+ and CD8+ T-cell responses to five HPV16 proteins (E6, E7, E4, L1 and L2) from a cohort of 41 women with varying grades of cervical disease." (PMID 15986031, 2005). "Using CD4- and CD8-enriched populations of responder cells isolated from 41 women with varying degrees of cervical disease, we have investigated the frequency and spectrum of HPV16-specific CD4+ and CD8+ T-cell responses, using ELISPOT assays of IFN-γ release, to HPV16 E4, E6, E7, L1 and L2." (PMID 15986031, 2005). "Our findings highlight the importance of early ART initiation (before reaching a low nadir CD4 cell count) and sustained effectiveness, as evidenced by duration, high adherence, virological control, and CD4 cell recovery, in controlling HPV infection and cervical disease progression." (PMID 29107561, 2018). "There is a partial disconnect between absolute CD4 count and CD4 percentage in HIV-1-positive women with cervical disease, where more women with ICC were grouped with low CD4 percentage, irrespective of absolute CD4 count that falls within the normal range." (PMID 32118737, 2020).
chronic heart failure (18 papers, 2013 to 2025). "Although her CD4 + counts improved, stabilizing between 0.44 and 0.83 × 109/L, she ultimately passed away at the age of 3 years due to chronic heart failure." (PMID 41288825, 2025). "Patients with congestive heart failure exhibit elevated pro-inflammatory CD4+ Th1 and Th17 cells alongside reduced anti-inflammatory T regulatory cells (Treg), correlating with disease severity." (PMID 38921319, 2024). "The current experimental results in animal models show that CD4+ T cells accumulated in the left ventricular tissue of mice with congestive heart failure and participate in collagen production through proliferation and activation." (PMID 36186992, 2022). "In congestive heart failure, both CD4+ and CD8+ T-cells are expanded and can both add to deterioration of the wound and wound healing." (PMID 34769184, 2021). "Unlike previous studies in chronic heart failure, where IL-10 was associated with a reduction in CD4+CD28null T cell frequencies, in ASCAD, its increase appears insufficient to counteract the inflammatory burden imposed by accumulated senescent T cells." (PMID 40508061, 2025). "Moreover, CD4+CD28null cells were found to be a strong and independent predictor of both all-cause mortality and cardiovascular mortality in patients presenting with chronic heart failure and AF, but were not predictive in patients free of AF." (PMID 34536081, 2021). "further describe increased populations of splenic and cardiac (left ventricle) F4/80 Ly6Clo macrophages, CD4+ cells—specifically CD4 + Foxp3+ regulatory T cells, and neutrophils in 12/15‐LOX KO mice in comparison to wild‐type mice in a model of chronic heart failure." (PMID 39659132, 2025). "In humans, previous studies found increased percentages of effector CD4+ T cells and central memory CD4+ and CD8+ T cells expressing CCR5 in patients with structural cardiopathy, but normal global ventricular function and no symptoms of chronic heart failure." (PMID 32393333, 2020).
coccidioidomycosis (18 papers, 2013 to 2026). A fungal infection caused by Coccidioides immitis. "In this case, the patient’s geographic history, combined with his advanced HIV status and CD4 count of 49 cells/mm3, placed him at particularly high risk for disseminated Coccidioides infection." (PMID 39835071, 2024). "Both clinical data and results of experimental animal studies have shown that T-cell immunity is essential for protection against coccidioidomycosis and mammalian hosts with deficiency of CD4+ T cells are at elevated risk of contracting the respiratory disease." (PMID 24367252, 2013). "Our patient presented with both of these high-risk features: a critically low CD4 count at the time of HIV diagnosis, a substantial viral load, and disseminated coccidioidomycosis necessitating amphotericin infusions." (PMID 39830540, 2024). "A small number of people with disseminated coccidioidomycosis have been found to have Mendelian mutations in the IL-12/IFN-γ pathway, evidence for the importance of IFN-γ and CD4 TH1 cells in immunity to coccidioidomycosis." (PMID 38535182, 2024). "Of the eight patients with HIV and a CD4 count less than 200 cells/mm3, six (75%) were ultimately diagnosed with coccidioidomycosis, and two (25%) were diagnosed with TB." (PMID 38248939, 2023). "A small number of people with disseminated coccidioidomycosis have been found to have mutations in the IFN-γ receptor or the IL-12 receptor, evidence for the importance of IFN-γ and CD4 TH1 cells in immunity to coccidioidomycosis." (PMID 32545735, 2020). "In this review, we focus on the recent progress in the characterization of CD4+ T-cell responses to Coccidioides infection." (PMID 28300772, 2017). "Human immunodeficiency virus infection is the most common cause for disseminated or extrapulmonary forms of histoplasmosis, coccidioidomycosis, and T. marneffei infection, particularly in patients with profound T-cell lymphopenia (CD4+ lymphocytes <200/μL)." (PMID 28702025, 2017). "Although CD4+ T cells are central to the mammalian protective response to Coccidioides infection, CD8+ T cells also mediate vaccine immunity." (PMID 24367252, 2013). "Vaccine-mediated CD4+ T-cell protection against Coccidioides infections may work best if the response is skewed, for example, to Th1 and/or Th17 immunity guided by an adjuvant." (PMID 28300772, 2017). "This plasticity of cellular immunity argues for the feasibility of developing a vaccine against coccidioidomycosis in patients with immune deficiencies, including those with few or no CD4+ T cells." (PMID 24367252, 2013). "For coccidioidomycosis, symptomatic infections are more likely in PWH with CD4+ counts below 250 cells/μL and those who are not virologically suppressed." (PMID 39459894, 2024).